CRP (C-reactive protein)
Diseases named in the same sentence as CRP in open-access papers (continued):
Sharing a sentence is not in itself a finding about the gene and the disease.
metabolic syndrome (continued). "We found that dyslipidemia after adjusting for age and disease activity and elevations of CRP and IL6 were the main factors negatively related to telomere lengthening in CS, even after controlling for other clinical and metabolic confounders." (PMID 25799396, 2015). "Metabolic syndrome was diagnosed in 273 patients (26.3%), whereas median CRP and albumin levels were 7 mg/L (range 1–23) and 4.4 g/L (range 2.6–5.8), respectively." (PMID 26496339, 2015). "Numerous studies have now confirmed that CRP levels are elevated in patients with the metabolic syndrome." (PMID 26366318, 2015). "In addition, our results showed that among smokers, CRP was associated with age while IL-6 was significantly associated with age, smoking variables as measured by years of smoking and number of pack-years, and dyslipidemia as measured by low HDL and high triglycerides levels." (PMID 26366318, 2015). "GWAS of the inflammatory biomarker C-reactive protein (CRP), identified several genes involved in metabolic syndrome, weight homeostasis, and premature atherothrombosis." (PMID 25853426, 2015). "A few studies have indicated relationships between elevated levels of inflammatory mediators, such as IL-6, TNF-α, and C-reactive protein levels, and metabolic syndrome." (PMID 25587268, 2014). "Male sex, BMI, triglycerides, CRP, tobacco smoking, metabolic syndrome and non-alcoholic fatty liver correlate negatively with adiponectin concentrations." (PMID 24693952, 2014). "We find that adjustment for covariates including CRP, metabolic syndrome factors and history of cardiovascular disease renders an association between total ALP and greater low grade albuminuria nonsignificant." (PMID 24505486, 2014). "Participants with metabolic syndrome had a higher mean CRP (5.3 versus 4.4 mg/dL; P = 0.45), insulin (18 versus 11 uIU/mL; P = 0.07), and BMI (32 versus 30 kg/m2; P = 0.45) compared to their counterparts." (PMID 25136359, 2014). "Previous studies, including our own, have reported that various cell types associated with atherosclerosis and metabolic syndrome produce PTX3 in response to inflammatory signals, while the liver elaborates most circulating CRP." (PMID 24705587, 2014). "As shown in our current study, in rats with hyperlipidemia producing by high-fat and high-cholesterol diet, 2 weeks of atorvastatin (10 mg/kg/day) therapy significantly improved dyslipidemia and reduced CRP level, which was consistent with previous finding." (PMID 24742015, 2014). "In patients with metabolic syndrome, after treatment with extended-release niacin (1 g/day) for 52 weeks, their endothelial function was improved by 22% and there was a decrease in CRP level by 20%." (PMID 24991087, 2014). "In the overall population, patients with higher levels of CRP were more likely to have a greater number of metabolic syndrome markers than those with lower levels of CRP." (PMID 24564178, 2014). "When C-reactive protein was included in the metabolic syndrome criteria, a larger percentage of black adults presented with the metabolic syndrome (42.2% and 34.3% respectively)." (PMID 25539758, 2014). "A total of 34.3% of patients with CRP levels ≥3 mg/L had 4 or 5 metabolic syndrome markers, compared with 14.5% of patients with CRP levels <1 mg/L." (PMID 24564178, 2014). "High plasma levels of CRP independently predict incident metabolic syndrome [22, pages 2016–2021], type 2 diabetes [23, pages 327–334], myocardial infarction [24, pages 1557–1565], and stroke, and variation in CRP is heritable [25, pages 1115–1122]." (PMID 25202455, 2014). "All parameters regarding CoQ10 status, CRP status as well as the parameters of metabolic syndrome defined by ATPIII were within a normal range." (PMID 24996614, 2014). "Group 3 seems to have characteristics of metabolic syndrome features, like WC, pulse pressure, and CRP." (PMID 25101128, 2014).
metabolic syndrome (continued). "Significantly higher values for waist circumference, C-reactive protein, uric acid, systolic blood pressure and triglycerides, and significantly lower values for high-density lipoprotein-cholesterol, were seen among the metabolic syndrome patients." (PMID 24714990, 2014). "Through IR the lypolysis is intensified in adipose tissue, creating atherogenic dyslipidemia which together with the production of cytokines by visceral adipose tissue promote inflammatory reactions and hepatic CRP synthesis." (PMID 23758779, 2013). "C-reactive protein levels reduced after a 12-week intervention for the group given n-3 and statins as compared to the control given statins only in patients with dyslipidemia." (PMID 31667003, 2013). "The objective of this study was to evaluate the antioxidative activity of mulberry leaf powder using DPPH assay and the effect of mulberry leaf powder on lipid profile, CRP level, and antioxidative parameters in mild dyslipidemia patients." (PMID 23484158, 2013). "In the present study, there were significant differences between ACS and non-ACS subjects with regard to conventional CAD risk factors like BMI, smoking pattern, dyslipidemia, family history of CAD, and C-reactive protein." (PMID 24386574, 2013). "Our findings indicate that the traditional markers of adiposity such as BMI or waist circumference remain superior markers for predicting metabolic syndrome compared to CRP, HMW-adiponectin, or the combination of both among the Japanese population." (PMID 24069195, 2013). "Previous population-based cross-sectional study confirmed that CRP levels gradually increase with increasing number of metabolic syndrome components (defined by the updated NCEP-ATPIII for Asian-Americans)." (PMID 24349092, 2013). "Although associations between CRP or HMW-adiponectin and metabolic syndrome have been well established, there have been few studies to examine the usefulness of combination of both biomarkers for prediction of metabolic syndrome." (PMID 24069195, 2013). "In this study, adjustment for CRP attenuated the effect of the metabolic syndrome by 35%, whereas adjustment of the effect of CRP for the metabolic syndrome did not reduce the size of effect." (PMID 23391158, 2013). "Recent clinical studies demonstrate LTα gene variability is also associated with metabolic syndrome features, including increased C-reactive protein, hyperinsulinemia, and dyslipidemia." (PMID 23704873, 2013). "Associations between CRP, HMW-adiponectin and development of metabolic syndrome after 4 years were assessed by logistic regression analysis and their predictive values were compared by receiver operating characteristic analysis." (PMID 24069195, 2013). "Odds ratios (95% CI) according to univariate and multivariate logistic regression analyses of HMW-adiponectin and CRP for development of metabolic syndrome." (PMID 24069195, 2013). "This research also reveals the tendency of mulberry leaf powder in reducing serum LDL and triglyceride as well as blood vessel inflammation stemmed from dyslipidemia, by the measurement of decreased CRP levels." (PMID 23484158, 2013). "In this study, we also showed that higher CRP and lower HMW-adiponectin were associated with future development of metabolic syndrome defined by either modified NCEP criteria or JASSO criteria." (PMID 24069195, 2013). "Combining the positive association of plasma CRP and TGF-β1 with BMI and possibly dyslipidemia, we propose that the positive association is a result of activation of the immune response, which warrants study of the mechanisms involved." (PMID 23826157, 2013). "In prospective studies, high hs-CRP levels have been shown to predict the metabolic syndrome, type 2 diabetes mellitus (T2DM) and coronary heart disease (CHD)." (PMID 23326306, 2013).
metabolic syndrome (continued). "In both men and women, blood pressure, triglycerides, HDL-cholesterol, C reactive protein, adiponectin, fasting glucose and insulin were significantly different in metabolic syndrome compared to non-metabolic syndrome individuals." (PMID 23028366, 2012). "Hs-CRP has limited capacity to predict the presence of the metabolic syndrome in a population with central obesity." (PMID 22417460, 2012). "Metabolic parameters including anthropometric variables, lipid profile, metabolic syndrome indices, C-reactive protein, fibrinogen and lipoprotein (a) [(Lp) (a)] were assessed for participants." (PMID 23351198, 2012). "Serum insulin, glucose, diastolic blood pressure, TG, leptin and CRP were significantly higher in metabolic syndrome group compared to obese and control groups." (PMID 22691465, 2012). "Elevated triglycerides and reduced HDL (i.e., atherogenic dyslipidemia) are usually accompanied by elevated apoB; CRP is a marker of inflammation that tends to be elevated in people with atherosclerotic conditions and metabolic syndrome." (PMID 22814200, 2012). "Metabolic syndrome, body mass index (BMI) and high-sensitivity C-reactive protein (hs-CRP) levels amongst the study participants (N = 324)." (PMID 29062730, 2012). "Patients with metabolic syndrome often present with higher levels of systemic inflammatory markers such as CRP, TNF-α, Fibrinogen and IL-6, and these markers are also increased in the blood of COPD patients." (PMID 22701684, 2012). "In conclusion, this study suggests that leptin and CRP are strong predictors of not only cardiovascular disease but also metabolic syndrome in Taiwanese men and women." (PMID 22533665, 2012). "After adjusting for age, CRP levels increased with increasing metabolic syndrome score in both male and female subjects (P < 0.001)." (PMID 22533665, 2012). "Rates of some CVD risk factors were higher in remote Indigenous Australians - central obesity (despite a lower BMI), dyslipidemia and CRP." (PMID 22455801, 2012). "Serum neutrophil elastase concentration is elevated in obese prehypertensive women and its level is correlated with inflammatory markers (high sensitivity C-reactive protein), dyslipidemia and air flow dysfunction." (PMID 21247478, 2011). "To date, only a few studies have investigated CRP variations in relation to the metabolic syndrome, with some providing null results, and the most recent reporting a significant association." (PMID 21296145, 2011). "In a large cohort consisting of men and women with known coronary artery disease, IL-18 was the only independent predictor of cardiovascular mortality in a subgroup with the metabolic syndrome, even after adjustment for CRP, IL-6 and fibrinogen." (PMID 20331890, 2010). "There was a linear increase in geometric means of hs-CRP with the increasing number of components of the metabolic syndrome in both sexes (P for trend < 0.001 for both men and women)." (PMID 20663138, 2010). "The relationship between metabolic syndrome and hs-CRP was examined using multivariate logistic regression analysis." (PMID 20663138, 2010). "Results of the current study showed significant correlation between metabolic syndrome and female sex, BMI, hs-CRP and left carotid artery IMT (P<0.05)." (PMID 22577415, 2010). "CRP has also been suggested as a predictor of cardiovascular events in patients with metabolic syndrome." (PMID 19222849, 2009). "Another study found that the incidence of metabolic syndrome was 14% in HIV-infected adults, and was associated with increased levels of leptin and C-reactive protein (CRP), and decreased levels of adiponectin." (PMID 19936197, 2008). "Increased levels of C-reactive protein (CRP) have been associated with inflammation, and CRP is recognized as a risk factor for CHD and metabolic syndrome." (PMID 17894873, 2007). "They found PAI1 contributed to a "metabolic syndrome" factor, whereas fibrinogen and CRP contributed to an "inflammation" factor." (PMID 18154661, 2007).
metabolic syndrome (continued). "A number of studies have demonstrated an association between glycemic load (GL) and levels of CRP, which is a powerful predictor for diabetes and CHD, and is positively associated with both insulin resistance and the prevalence of the metabolic syndrome." (PMID 15530168, 2004). "Consistently, pioglitazone, a PPAR-γ agonist, has been reported to reduce depressive symptoms in MDD patients with metabolic syndrome, particularly among those with elevated CRP levels, and to improve affective and motivational deficits when added to standard therapy in bipolar depression." (PMID 41479556, 2026). "Elevated CRP levels are also associated with increased risks of metabolic syndrome and cardiovascular events independent of traditional risk factors." (PMID 41301855, 2025). "Although observational studies suggested a positive correlation between hs-CRP and dyslipidemia, the MR analysis did not support the direct causation between elevated hs-CRP and dyslipidemia." (PMID 39859220, 2025). "Notably, CRP provided additional predictive value for cardiovascular events even among those already diagnosed with metabolic syndrome." (PMID 40943152, 2025). "Cardiovascular risk was elevated in those with high CRP levels (≥3.0 mg/L), regardless of the number of metabolic syndrome traits." (PMID 40943152, 2025). "When both CRP and dyslipidemia were adjusted, good OHS was significant with HR = 0.51, p = 0.05)." (PMID 39860376, 2025). "Despite the observational evidence linking hs-CRP to dyslipidemia, the MR analysis did not confirm a direct causal effect." (PMID 39859220, 2025). "GlycA (Nuclear Magnetic Resonance) integrates acute-phase glycoproteins; along with cluster of differentiation 163 (sCD163) and calprotectin, it outperforms high-sensitivity C-reactive protein (hs-CRP) for low-grade inflammation and predicts metabolic syndrome and coronary calcification." (PMID 41235333, 2025). "After adjusting for age, sex, education level, marital status, BMI, dyslipidemia, heart disease, stroke, smoking status, drinking status, lipid-lowering drugs, hypoglycemic drugs, HbA1c, and CRP, the proportion of mediators of eGFR was elevated (Adjusted for 6.00% vs. 3.14%)." (PMID 40017692, 2025). "Based on the decision tree regression, there were more variables that indicated clinical suspicion of SLD in women (BMI ≥29 kg/m2, age ≥50 y, dyslipidemia, MS, hs-CRP ≥0.195, low HDL-c <42, and NC ≥36 cm) than in men (waist circumference ≥101, ALT ≥28, HbA1c ≥5.7%)." (PMID 40531757, 2025). "In parallel, the Mediterranean pattern provides an intrinsic anti-inflammatory component: reductions in hs-CRP/IL-6 in metabolic syndrome, and even isocaloric CRP decreases (−26.1% in 5 weeks) without weight loss." (PMID 41305609, 2025). "Third, the absence of key clinical covariates, such as body mass index (BMI), metabolic syndrome components, and systemic inflammatory markers (e.g., CRP, IL-6), may have led to residual confounding." (PMID 40868344, 2025). "This shows that fecal arachidonic acid in IBD is associated with inflammation-induced dyslipidemia rather than the routinely measured marker of inflammation, CRP." (PMID 40362272, 2025). "Moreover, vitamin D downregulates inflammatory markers such as C-reactive protein (CRP) and TNF-α, reducing systemic inflammation linked to metabolic syndrome." (PMID 40356969, 2025). "In addition, patients with psoriatic disease have higher levels of resistin, C-reactive protein (CRP), and cytokine macrophage inflammatory protein (CMIT), which leads to an increased risk of cardiovascular disease and metabolic syndrome." (PMID 40724556, 2025). "Therefore, in the presence of dyslipidemia, males and females had higher IL-6 and lower adiponectin serum concentrations, whereas higher CRP was observed only in males." (PMID 39936780, 2025).
metabolic syndrome (continued). "To date, biomedical risk factors such as obesity, cholesterol, C-reactive protein, blood-pressure level, and metabolic syndrome (MetS), as well as lifestyle (e.g., physical inactivity, smoking, alcohol consumption, unhealthy diet) and psychological variables have been studied extensively." (PMID 39698381, 2024). "Baseline characters of participants grouped by elevated CRP levels and dyslipidemia." (PMID 39247228, 2024). "The objective of this study was to examine whether the combination of elevated levels of C-reactive protein (CRP) and dyslipidemia increased the risk of stroke among middle-aged and older adult individuals in China." (PMID 39247228, 2024). "Furthermore, increased CRP values are associated with various diseases, particularly CVD, DMT2, and metabolic syndrome." (PMID 39021797, 2024). "The study population was further divided into four groups based on normal or abnormal C-reactive protein levels and whether they had dyslipidemia." (PMID 39247228, 2024). "Vitamin D status showed a different relationship with dyslipidemia compared with CRP." (PMID 39200151, 2024). "A meta-analysis of 16 case–control studies in recent years showed that quercetin supplementation is associated with lower levels of total cholesterol (TC), low-density lipoprotein (LDL), and C-reactive protein (CRP) in patients with metabolic syndrome and related disorders." (PMID 39456969, 2024). "The significant correlations observed for VLDL, IDL, and LDL in both groups were rendered insignificant after adjusting for age, sex, body mass index (BMI), waist circumference, or metabolic syndrome severity score (MetSSS) as well as for age, sex, BMI, and C-reactive protein (CRP)." (PMID 38732266, 2024). "Elevated CRP in adolescence is also associated with increased risk for many negative health outcomes and correlates including metabolic syndrome, elevated BMI, and persistent elevations in inflammation into adulthood." (PMID 38136035, 2023). "Moreover, bilberry also showed its ability to decrease serum C-reactive protein (CRP), IL–6, IL–12, and LPS levels, and lowered genes linked with the TLR pathway in individuals who presented with metabolic syndrome." (PMID 36838522, 2023). "We and some other clinical investigations have documented the correlation between various factors, including cardiac troponin, age, sex, thyroid hormones, LVEF, metabolic syndrome, hyperglycemia, total bilirubin, creatinine, TC, and C-reactive protein with worse outcomes in MINOCA." (PMID 36647062, 2023). "Moreover, it has been reported that patients with T2D and metabolic syndrome have increased IL-1RA levels, and these are positively correlated with CRP, BF (%) and weight gain." (PMID 36771387, 2023). "In the current study, we analysed the effects of beetroot on parameters of glucose and lipid metabolism in two models of metabolic syndrome: (i) transgenic spontaneously hypertensive rats expressing human C-reactive protein (SHR-CRP rats), and (ii) hereditary hypertriglyceridemic (HHTg) rats." (PMID 36837811, 2023). "However, we found a negative correlation between gal-2 and HDL concentration which is consistent with its role in the promotion of dyslipidemia, as well as a positive correlation with CRP." (PMID 37892153, 2023). "Dyslipidemia together with a proinflammatory status characterized by increased levels of CRP, fibrinogen, cytokines, and other biomolecules is mutually connected with PD through bidirectional interactions as suggested by numerous cross-sectional and longitudinal prospective clinical studies." (PMID 36983201, 2023). "For example, CRP has long been considered a risk factor for schizophrenia, exhibiting positive correlations with cognitive impairment, negative symptoms, and metabolic syndrome in SCZ patients." (PMID 37600668, 2023). "Moreover, liver steatosis and elevated us-CRP in addition to dyslipidemia and overweight indicated that not only a NAFL, but possibly a NASH cohort had been recruited." (PMID 36769628, 2023).